DNMT3A (DNA methyltransferase 3 alpha)
Diseases named in the same sentence as DNMT3A in open-access papers (continued):
Sharing a sentence is not in itself a finding about the gene and the disease.
tumor (continued). "Fabbri and co-workers revealed that the miR-29 family (29a, -b, and -c) act as tumor suppressor miRs in lung cancer and regulate transcript levels of DNMT3A and DNMT3B." (PMID 32906681, 2020). "The tumors were resected and processed for immunohistochemical staining; the results revealed that treatment with the LV-miR-199a-3p construct resulted in the decreased expression of RAP2a and DNMT3a in tumor tissues." (PMID 33365310, 2020). "We examined the expression levels of 3 DNMTs, namely Dnmt1, Dnmt3a, and Dnmt3b, that are key enzymes regulating DNA methylation in specific genes, including tumor suppressor genes." (PMID 30940675, 2019). "There are currently only four reported cases of an AML tumor carrying the DNMT3A p.Arg771Gln substitution." (PMID 31160375, 2019). "The protein expression levels of the pyroptosis-related protein GSDME and DNA methyltransferases (Dnmt1, Dnmt3a, and Dnmt3b) in tumor tissues were evaluated by western blotting to explore the mechanism of the in vivo antitumor activity of As2O3-NPs." (PMID 31637008, 2019). "DNA methylation, mediated by the combined action of three DNMTs (Dnmt1, Dnmt3a and Dnmt3b), has a particularly prominent role in tumor initiation, progression and specific tumor cell subsets." (PMID 31492191, 2019). "It was shown that SETDB1 and DNMT3a directly interact and localize at the promoter regions of tumor suppressors and induce heterochromatin formation and gene silencing." (PMID 31405032, 2019). "The expression level of three DNA methyltransferases including DNMT1, DNMT3a and DNMT3b increased and the expression level of Tet ten-eleven translocation protein 2 remarkably decreased in tumorous spleens." (PMID 29849932, 2018). "Patients that show overexpression of DNMT3A or DNMT3B (z-score ≥ 2) in the tumor sample are shown in dark green." (PMID 30468428, 2018). "Previous studies have found that the methyI-H3K9-binding protein MPP8 enhances tumour cell motility and invasion properties by interacting with DNMT3A." (PMID 29717263, 2018). "DNMT3A is also reported as one of the critical tumor suppressor genes, has crucial biological role in self-renewing cells, enabling their differentiation." (PMID 29876008, 2018). "On the other hand, when we took into account the tumor expression profile, DNMT3A overexpression was significantly correlated with BCL2 protein expression (P = 0.0261)." (PMID 29721185, 2018). "High-mobility group A2 protein, HMGA2, fosters the binding of DNMT3A to the E-cadherin promoter and the removal of epithelial features by tumour cells." (PMID 29717263, 2018). "Immunohistochemistry analysis of DNMT3A in 31 DLBCL samples showed that DNMT3A overexpression (>42% of positive tumor cells) correlated with reduced overall and event-free survival." (PMID 29721185, 2018). "In DLBCL samples, the percentage of DNMT3A-positive tumor cells varied between 0% and 100% and the percentage of DOT1L-positive tumor cells between 1% and 85%." (PMID 29721185, 2018). "In the first patient we analyzed, we show that the DNMT3A single-mutant subclone was present at only 1.7%, when the bulk sequencing predicted it to comprise 23.6% of the tumor at diagnosis." (PMID 30087104, 2018). "To this end, we isolated by FACS-based cell sorting the basal integrin α6bright tumor cells from four wild-type and eight Dnmt3a-cKO tumors, and performed whole-genome transcriptome profiling by RNA-seq." (PMID 28425913, 2017).
tumor (continued). "The first epidermal squamous malignancies appeared significantly sooner in Dnmt3a-cKO than in their wild-type littermates, after only 2 months from the first DMBA treatment, indicating that Dnmt3a acts as a barrier against tumor initiation." (PMID 28425913, 2017). "In female mice, in utero exposures to SHS up-regulated the protein expression of DNMT3A 5.5 fold compared with air controls, suggesting hypermethylation, which is related to silencing of tumor suppressors." (PMID 28651580, 2017). "RHOA mutations were identified only in PD1+ cells in 100% cases, while TET2 and DNMT3A mutations were identified in both the PD1+ cells and CD20+, tumor-cell-depleted cells in the majority of cases." (PMID 28157189, 2017). "Using knockout mouse models, we now have demonstrated that Dnmt3a is also tumor-suppressive toward carcinogen-induced epidermal squamous neoplasia." (PMID 28425913, 2017). "Inhibition of DNMT1, DNMT3a and DNMT3b has been reported to prevent tumor growth in many types of cancers." (PMID 28926997, 2017). "A variety of experimentally validated target genes regulated by hsa-miR-31-5p has been described in different tumor types, including AR and DNMT3A genes." (PMID 28122331, 2017). "Chemotherapy treatments also affected the levels of DNMT1 and DNMT3A in the PFC tissues of tumor-bearing animals." (PMID 28758896, 2017). "Currently, DNMT3A abnormalities are the most common subject in the field of epigenetic medical research, because of its significance in tumor pathogenesis and the potential for target medication." (PMID 28127428, 2017). "We found that DDX3 knockdown enhanced protein level and DNA binding of DNMT3A as well as DNA methylation on promoter regions of these tumor-suppressive miRNAs, which results in suppressing transcription of these miRNAs." (PMID 27344963, 2016). "Altogether, these data suggest that Dnmt3a is a tumor suppressor gene in prevention of CLL and PTCL in mice." (PMID 27690235, 2016). "MTHFR shows higher methylation levels in tumor tissue respect to blood (p = 0.007), and DNMT3A shows about 10% promoter methylation in tumor tissue but is completely demethylated in blood (p < 0.0001)." (PMID 27999265, 2016). "Despite these last two examples, the overwhelming body of work in the field suggests that Dnmt3a acts as a tumor suppressor in various types of hematologic malignancies." (PMID 27563627, 2016). "For DNMT3A, higher methylation levels in the healthy tissue adjacent to a tumor were observed with respect to blood." (PMID 27999265, 2016). "Altogether, our data demonstrate that Dnmt3a is a haploinsufficient tumor suppressor in the prevention of CD8+ T cell transformation and highlight the importance of understanding of the roles of Dnmt3a target genes in disease pathogenesis." (PMID 27690235, 2016). "This allowed us to assess the extent of DNA hypomethylation and effect on tumor growth controlled by negative regulation of DNMT3A by UHRF1/2." (PMID 27462454, 2016). "Altogether, these results show that the Dnmt3a’s tumor suppressor function in prevention of CLL resides within the hematopoietic compartment and is likely cell-autonomous." (PMID 27677595, 2016). "Taken together, these data clearly show that Dnmt3a and Dnmt3b possess tumor suppressor functions in the prevention of the vast majority of hematologic malignancies." (PMID 27563627, 2016). "Abrogating this negative regulation on DNMT3A or overexpression of DNMT3A leads to increased DNA methylation and impaired tumor growth." (PMID 27462454, 2016). "DNMT1 was well distributed in the cytoplasm and nuclei of tumor cells or glands, while DNMT3a and 3b were well distributed only in the cytoplasm, as shown by staining a dark brown color." (PMID 25823664, 2015).
tumor (continued). "Our results indicate that the engineering of artificial DNA-binding domains (DBDs) linked to DNMT3A can be utilized to promote long-lasting SOX2 silencing and represents a promising therapeutic approach to minimize tumor relapse." (PMID 25684141, 2015). "The tumor volume was significantly smaller in BGC-shDNMT3A cell-injected nude mice (7.5 ± 9.23 mm3) than in BGC-shControl cell-injected mice (159.5 ± 151.26 mm3; P < 0.05), indicating that DNMT3A has a critical function in tumor growth." (PMID 26350239, 2015). "Increased protein levels of CK20, E-cadherin, and DNMT3a was observed after tumor DNA treatment in HT-29 cells." (PMID 26133168, 2015). "The results revealed that DNMT3A overexpression was strongly correlated with tumor cell differentiation." (PMID 26350239, 2015). "The average expression level of DNMT3A in the tumor tissues was significantly higher than that in the paired adjacent non-tumor tissues (0.68 versus 0.39; P < 0.05)." (PMID 26350239, 2015). "Compared with the paired adjacent non-tumor tissues, DNMT3A was overexpressed (defined as a greater than a 2-fold increase) in 22 of the 35 (63%) samples, according to the western blot data." (PMID 26350239, 2015). "Surprisingly, the mean levels of DNMT1, DNMT3a, and DNMT3b overexpression have turned out to be quite similar among different tumor types." (PMID 24822169, 2014). "On the other hand, the somatic mutations in DNMT3A and ASXL1 are of the type previously observed in other tumor types and expected to contribute to tumorigenesis." (PMID 25000259, 2014). "Other targets of up regulated miRNAs in different treatment conditions also includes proteins that inhibit tumor progression, such as DNMT3A, FADD, pTEN, FOXO3, DDX20 and PA2G4 (EBP1)." (PMID 24387052, 2014). "Recently, more reports have shown that miR-29 family regulated tumorigenesis and tumor progression by targeting DNMT3A, DNMT3B, TIAM1, cyclin E, MMP2, ID1, SPARC and COL3A1." (PMID 23936390, 2013). "A mouse tumor model showed that a functional DNMT3a determined that genomic hypomethylation was restricted to regional rather than the uniformly widespread hypomethylation throughout the genome that occurs in DNMT3a deficient mice." (PMID 24363660, 2013). "With three catalytically active DNMTs in humans and the finding that DNMT3A acts as a tumor suppressor, isozyme selectivity of DNMT inhibitors is important." (PMID 24236046, 2013). "We have established genome-wide methylation profiles at single base pair resolution to define Dnmt3a-dependent methylation changes in a mouse tumor model." (PMID 23284304, 2012). "Statistical analysis also suggested Dnmt3a, Itga6, and Shc1, however high fold changes were measured for these genes in tumor cells." (PMID 21464922, 2011). "Taken together, our findings confirmed that miR-143 regulates DNMT3A expression and has a tumour-suppressive role in CRC development." (PMID 19638978, 2009). "Restoration of the miR-143 expression in colon cell lines decreased tumour cell growth and soft-agar colony formation, and downregulated the DNMT3A expression in both mRNA and protein levels." (PMID 19638978, 2009). "Histological analyses from knockout mice indicated that the loss of Dnmt3a triggers tumorigenesis through the upregulation of the adipogenesis regulator PPARγ, while the absence of Dnmt3b facilitates tumour growth and metastasis." (PMID 39846570, 2025). "Furthermore, these enzymes are considered tumor suppressors in certain tissues and oncogenes in others, while DNMT3A and DNMT3B have occasionally opposite effects." (PMID 39819598, 2025). "Also, elevated global DNA methylation levels and increased expression of DNA methyltransferases (DNMT1, DNMT3A, DNMT3B) have also been linked with poor prognosis and higher tumor aggressiveness." (PMID 41150792, 2025).
tumor (continued). "In solid tumor (including glioma) CAR-T models, DNMT3A deficiency boosted CAR-T expansion, cytokine secretion, and lysis; after chronic stimulation, these cells showed higher TCF1/LEF1 and stem/naive-like epigenetics, increasing in vivo anti-tumor activity." (PMID 40927709, 2025). "In recent years, DNMT3A has been intensely studied for its role in tumor prognosis and therapy." (PMID 41450820, 2025). "mTORC2 integrates aberrant RTK signaling with environmental nutrient levels to regulate histone modifications and promote tumor growth, driving the hypomethylator phenotype by epigenetically regulating DNMT3A, which in turn remodels the tumor-supportive glutamate metabolism network." (PMID 40565099, 2025). "In addition, our IHC analysis showed that the expression of DNMT3a in LUAD tissues was significantly higher than that in adjacent non-tumour tissues, and high expression of DNMT3a was positively correlated with high TNM stage and poor tumour differentiation." (PMID 39990668, 2025). "Based on these results, the DNMT3a-mediated epigenetic regulation mechanism can be correlated with the occurrence, malignant progression and drug resistance of different tumours and could be a novel prognostic biomarker." (PMID 39990668, 2025). "In addition, increasing variant allele frequency (VAF) of recurrent mutations, includingTET2, RHOAG17V, DNMT3A, IDH2R172, and PLCγ1 observed in several models over passage, indicate clonal expansion or tumor cell enrichment in subsequent passages." (PMID 40510016, 2025). "In other cases, however, TET2, DNMT3A, and TET3 variants, appeared to be tumor specific." (PMID 40510016, 2025). "Taken together, these findings indicate that DNMT3A and GMPS exert context-dependent effects that are closely linked to the TME and immunogenomic landscape of each tumor type, emphasizing their potential as biomarkers for patient stratification and precision immuno-metabolic therapies." (PMID 41465346, 2025). "Furthermore, we identified that Diazinon binds to DNA methyltransferases (DNMT3A/3B) and inhibits their activity, thereby playing a tumor suppressor role by increasing the expression of TAT in BC." (PMID 39334853, 2024). "We hypothesized that DNMT3A may also suppress chemokines to discharge lymphocytes from evolving tumor regions." (PMID 37847338, 2024). "Next, we assessed DNMT3A protein expression in a tissue microarray containing 128 paraformaldehyde‐fixed GBC tumor tissues using immunohistochemistry and evaluated the relationship between the expression level of DNMT3A and different clinicopathological characteristics in patients with GBC." (PMID 38380551, 2024). "Our findings indicate that DNMT3A-mediated epigenetic silencing of LDHB may contribute to HCC progression through remodeling the tumor immune microenvironment, and LDHB may become a potential prognostic biomarker and therapeutic target for HCC immunotherapy." (PMID 38739169, 2024). "Therefore, the aim of this study was to identify DNA sequence variation in DNMT1 rs2228611, rs2228612 and DNMT3A rs2276598, rs752208, as well as to investigate their effect on the tumor phenotype and disease prognosis in BC patients." (PMID 39597087, 2024). "We identified several pathways that shifted during transformation, and the transformation might be promoted by epigenetic alterations (such as HDAC10, HDAC1, DNMT3A) within the tumor cells instead of within the tumor microenvironment." (PMID 39353908, 2024). "Tumor NGS results were still pending, and his liquid biopsy (FoundationOne® Liquid CDx; Foundation Medicine, Inc., Cambridge, MA, USA) showed a low ctDNA tumor fraction (<1%) and detectable mutations in DNMT3A and TET2 suspicious for clonal hematopoiesis." (PMID 39449891, 2024). "In conclusion, the overexpression of miR-532-3p could suppress proliferation, invasion, and migration of PC cells, as well as tumor formation in nude mice through inhibiting the methylation of SOCS2 by targeting DNMT3A." (PMID 37085288, 2023).
tumor (continued). "DNMT3A deletion also appears to enhance the anti-tumor effects of T-cells whether in the context of immune-checkpoint inhibition, chimeric-antigen receptor (CAR) T-cells, or allogeneic HSCT." (PMID 37325668, 2023). "Furthermore, we determined the expression of the members of the DNA methyltransferase family (DNMT1, DNMT3a, and DNMT3b) in tumor tissue by immunohistochemistry." (PMID 37175434, 2023). "Interestingly, a recent IHC study also analyzed the protein expression of DNMT1 and DNMT3A in relation to tumor stage." (PMID 37367043, 2023). "In addition to known driver mutations in DNMT3A and IDH1, one patient also had missense tumor specific mutations in the FANCA and FANCM genes." (PMID 36382570, 2023). "Intriguingly, robustly higher levels of DNMT3A and 3B were observed in these tumors and their increased expression may rescue global DNA hypomethylation to circumvent its tumor suppressive effect." (PMID 37388735, 2023). "Thus, we concluded that DNMT3A was involved in the PC cell proliferation and metastasis, as well as tumor growth." (PMID 37085288, 2023). "Knockdown of Linc00942 reduces DNMT3a expression and genome‐wide DNA methylation while Linc00942 overexpression increased DNMT3a expression and correlated hypermethylation in cancer cells and primary tumour tissues." (PMID 37477089, 2023). "Thus, the tumor suppressive function of aging-like DNA hypomethylation is severely impaired in hDNAmad+ tumors, likely due to enhanced expression of DNMT3A/3B and dysregulated aging regulators." (PMID 37388735, 2023). "Moreover, ELFN1-AS1/EZH2/DNMT3a affected tumor growth and oxaliplatin resistance by regulating MEIS1-FEN1." (PMID 35351858, 2022). "Tumor xenograft in nude mice was carried out to study whether miR-34a-5p/c-MYC/DNMT3a axis regulates CRC in vivo." (PMID 34623601, 2022). "Notably, recipients of Dnmt3a-KO T cells exhibited superior tumor control and/or eradication as compared with recipients of WT T cells, and this potent antitumor response was associated with improved tumor-free survival." (PMID 35608905, 2022). "Mechanistic studies with epigenetic and transcriptomic profiling showed that MLL4 promotes activation of both typical and super enhancers to increase the expression of their nearby genes, including the RISC component Ago2 and the DNA methyltransferases Dnmt1 and Dnmt3a in tumor cells." (PMID 36323669, 2022). "Moreover, DNMT3A elevated in NSCLC tumor tissues compared to adjacent normal tissues as well as in NSCLC cell lines compared to BEAS2B." (PMID 35860691, 2022). "Here, we demonstrated DNMT3A-mediated SFRP1 methylation promoted tumor progression in NSCLC." (PMID 35860691, 2022). "In concordance, the deletion of DNMT3A in a mouse model promotes LUAD tumor growth and progression." (PMID 35205708, 2022). "Moreover, in this group, overexpression was found in several tumor oncogenic genes (such as CCND1, MDM2, MDM4, and DNMT3A), which positively associated with hyperprogression, which led to ICB-related high progression of the disease." (PMID 35909893, 2022). "Many studies have shown that METTL3 promotes tumor growth and aggressiveness by regulating the mRNA decay and stability or mRNA translation of numerous tumor-associated genes, such as SOCS2, BATF2, EGFR, TAZ, MAPKAPK2, and DNMT3A." (PMID 35456475, 2022). "Here, analysis of the correlation between CARM1 and four methyltransferases (DNMT1, DNMT2, DNMT3a, DNMT3b) expression was conducted for each tumor to explore whether CARM1 expression is related to epigenetics." (PMID 35033016, 2022). "Additionally, gene enrichment analysis showed that low DNMT3A expression was related to ribosomal processing, an essential part of tumor survival." (PMID 34471186, 2021).